TLR2 (toll like receptor 2)
Diseases named in the same sentence as TLR2 in open-access papers (continued):
Sharing a sentence is not in itself a finding about the gene and the disease.
infection (continued). "However, TNF-α was still expressed in TLR2-/- cells at approximately 50% of the level seen in wild-type cells, and it is possible that immune mediators such as TNF-α produced early in infection, might induce apoptosis." (PMID 17470292, 2007). "Conversely, in TLR2 or TLR4 deficient mice acute, but not chronic infection is controlled." (PMID 16285886, 2005). "This study aims to elucidate the potential contribution of TLR2-mediated innate immunity to H. pylori-related disease outcomes and to explore possible sources of heterogeneity such as ethnicity, genotyping methods, and infection status (e.g. cagA-positive vs. negative strains)." (PMID 41503064, 2025). "However, upon intravenous infection we could not find evidence for a role of TLR2 during acute MHV68 infection." (PMID 37065193, 2023). "However, TLRs may be less prominent or less responsive in the intestinal environment or may be “model dependent” as deficiencies in TLR2 and TRL4 did not increase infection in a neonatal mouse model." (PMID 37325809, 2023). "However, no increase in IL-6 levels was observed for infection of the TLR2−/− BMMs." (PMID 37404047, 2023). "In the presence of TLR2-rs5743708 and/or TLR4-rs4986791 polymorphisms, reduced binding affinity for E and S proteins, respectively may explain the inadequate immune response against SARS-CoV-2 that fails to control infection, worsening the disease outcome." (PMID 37766191, 2023). "While we propose that PPE51 exerts its functions mainly as a TLR2 antagonist, it could be proposed that a bacterial advantage exists if Mtb produces both agonistic and antagonistic TLR ligands, perhaps at different stages of infection or in different host microenvironments." (PMID 35467412, 2022). "Notably, SPexp mice had increased frequencies of TLR2+ and TLR4+ leukocytes, consistent with observations in microbially experienced laboratory mice CoH with pet store mice, cumulatively demonstrating that sequential infection alters the activation status of multiple cell types." (PMID 35878936, 2022). "Although LPS is widely known to be the PAMP recognized by TLR4 following infection by a range of Gram-negative pathogens, prior experimental assessments of L. pneumophila on this particular topic were murine-based and they had concluded that TLR2 is the receptor responding to L. pneumophila LPS." (PMID 34280250, 2021). "However, the induction of pro-inflammatory mediators only functions to keep bacterial growth in check, as evident by heightened bacterial burdens in TLR2 and caspase-1 KO mice, but does not lead to infection clearance, since biofilms remain chronic in the WT setting where both molecules are present." (PMID 32290861, 2020). "Similarly, E. coli K88 and mycotoxin zearalenone (ZEA) infection of IPEC-1 epithelial cell line was protected in the presence of mixed Lactobacillus strains (L. acidofilus ID11692, L. plantarum ID1253 and L. paracasei ID13239) by downregulating TLR-1, TLR-2 and TLR-4 gene expression." (PMID 32045425, 2020). "Interestingly, we could not see any involvement of TLR2 or TLR3 nor suppression of infection by IFN-β production." (PMID 31867020, 2019). "TLR-2 levels were more upregulated by Nc-Spain1H infection than by Nc-Spain7 infection in both cell lines, which led us to hypothesize that the high-virulence isolate would activate less of the TLR recognition system, reducing the immune responses triggered by TLR-2." (PMID 31068227, 2019). "Thus, diverse bacteria responsible for infections which may be relevant to MS, of both Gram-positive and Gram-negative origin, are potent triggers of TLR2 signaling." (PMID 29593720, 2018). "Furthermore, most of the pro-inflammatory genes found on this array, which we have previously identified to be increased with 22L infection (such as Cxcl10, Ccl8, Tnf, IL1a, and IL1b), were similarly increased in the absence of TLR2 or C5aR1 signaling during scrapie infection." (PMID 30596651, 2018).
infection (continued). "Therefore the effect of TLR2 on enhanced infection is independent of viral entry." (PMID 30520725, 2018). "However, no eggs were found in the faeces of the TLR2 wild-type and mutant mice after infection." (PMID 28784165, 2017). "However, TLR2 gene expression might be already at high levels in these mice and does not further increase during infection." (PMID 28428684, 2017). "Accordingly, the DAMP and/or TLR2 hypothesis can both explain the ROS dysregulation observed in eRA although cell samples were collected in periods without any clinical symptoms of an infection and without any routine laboratory signs of inflammation." (PMID 29259607, 2017). "We have previously shown that CD8+ T cells are involved in the control B. microti infection in vivo as well as in macrophages in vitro and, thus, defective control of infection observed in the absence of TLR2 and TLR4 could be related with a lower generation of B. microti-specific CD8+ Tc cells." (PMID 28119856, 2016). "In vitro infection of mouse bone marrow-derived monocytes (BMDMs) with Ft revealed that by 24 h of co-incubation ∼1.5-log more total bacteria (intra- and extracellular combined) were recovered from TLR2−/−, but not CD14−/−, cells compared to wild-type cells (data not shown)." (PMID 23554897, 2013). "Furthermore, L-ferritin was not regulated by the infection in TLR-2-/- BMM." (PMID 24349383, 2013). "In addition, we found abrogation – or almost complete suppression – of infection by pseudoviruses containing the BaL or BR envelope glycoproteins in MDMs stimulated through TLR3 or TLR4, with only partial reduction observed in cells stimulated through TLR2, TLR7 or TLR9." (PMID 23028330, 2012). "Thus, the absence of TLR2 and 4 reduces IFNγ release in the lymph nodes and lungs and lymph node T-cell proliferation that correlate with increased severity of Chlamydia respiratory disease and infection in early life." (PMID 22724018, 2012). "However, we show that in the absence of TLR2 both infection and neutrophil levels are increased." (PMID 22724018, 2012). "However, an ongoing infection with gram-negative bacteria might sensitize the lung towards gram-positive stimuli as TLR2 and TLR6 expressions are upregulated by LPS." (PMID 21547259, 2011). "Furthermore, TLR2 and the TLR adaptor protein MyD88 are critical for host defense against Francisella infection since mice lacking these proteins are more susceptible to infection than their wild-type counterparts." (PMID 21698237, 2011). "Due to the sequential activation of TLR2 and the AIM2 inflammasome during F. novicida infection of macrophages and the critical role that both of these recognition systems play in host defense against this bacterium, we tested whether these systems cooperate during infection." (PMID 21698237, 2011). "However, in contrast to a previous report, we show that the requirement for TLR2 is independent of the route of infection, since TLR2−/− mice had significantly decreased survival rates compared to controls following infection by either the intranasal or the intradermal route." (PMID 19936231, 2009). "Bacterial numbers in CSF were similar in all strains 24 h after infection (data not shown), indicating that planctonic bacteria recovered in CSF did not represent an early pathogenetic factor, which contributed to the more severe clinical picture of the TLR2-/- strain." (PMID 17428319, 2007). "A limitation of this study is the lack of in vivo validation of the role of hepatocyte TLR2:TLR6 and TLR5 in mediating the hepcidin response and subsequent hypoferremia during infection." (PMID 40182015, 2025). "After NTHi infection, the TNFα expression was similar in TL2-C29-treated as in MDM controls, indicating that TLR2 does not mediate the expression of TNFα in NTHi-infected MDMs." (PMID 40013145, 2025).
infection (continued). "Since HEK-293 cells express neither TLR2 nor TLR4, these data suggest that the improved release of IL-8 by Caco-2 in response to the infection with M90T ΔvirK and ΔybjXΔvirK derivatives likely relies on the activation of the TLR signaling pathways." (PMID 41144768, 2025). "Despite that TLR2 levels were not induced by PA either in smokers or COPD patients, BUD and FLU cotreatment during PA infection rescued the response to PA increasing TLR2 levels in the same groups of patients (p < 0.05)." (PMID 35897707, 2022). "Vaccine engagement of innate immunity via ligands to TLR2 or TLR4 or presentation via virus-like particles elicited robust, protective immunity in the absence of post-infection inflammatory responses including pulmonary eosinophilia." (PMID 36560488, 2022). "This analysis revealed that all genotypes had increased osteoclastogenesis from infection; however, WT cells incurred significantly greater infection-induced osteoclastogenesis than did cells lacking TLR2, TLR9, or TLR2/9." (PMID 36226943, 2022). "We found that infection of human MDMs with both CHIKV wild type and UV-CHIKV induced a high expression of TLR2 mRNA at 6 hpi, without significant differences between CHIKV- and UV-CHIKV-infected MDMs." (PMID 35223841, 2022). "This manifested in vivo as heightened TLR2-dependent inflammatory cytokine secretion (irrespective of bacterial CFU) and dramatically disrupted infection burden in the livers of mice infected with a BCFA auxotroph, but not WT S. aureus." (PMID 34496007, 2021). "One study has described TLR2 activation in O. tsutsugamushi-infected mice and cultured HEK293 cells and others identified no role for TLR4 in mice during infection." (PMID 34320039, 2021). "After infection with E. chaffeensis, MIP-2 (CXCL2) and TNF mRNA induction in murine bone marrow derived macrophages was MyD88-dependent, but did not require TLR2 or TLR4." (PMID 33747981, 2021). "have shown that the expression of TLR2, TLR4 and MyD88 did not change in bovine macrophages after 6 h of infection with M. bovis in relation to the non-infected control." (PMID 34335572, 2021). "TLR2, TLR3, TLR9, and TLR13 expression patterns showed no significant variations in mRNA expression in koala PBMCs with a range of subtype infection profiles (KoRV-A only vs. KoRV-A with KoRV-B and/or -C)." (PMID 33915914, 2021). "As previously reported, MyD88 KO mice did not control LVS infection; further, using this dose and route of infection, LVS control was only modestly dependent on TLR2 and TLR9." (PMID 32745117, 2020). "Moreover, although a Listeria monocytogenes lgt mutant fails to activate TLR2 signaling it is significantly less virulent in a mouse infection model, whereas lgt mutants of Streptococcus agalactiae and Staphylococcus aureus are hypervirulent in mouse infection models." (PMID 32849426, 2020). "The variant was a cis-eQTL for IFNB1 after activation of the TLR1/TLR2, TLR4, and TLR7/TLR8 pathways, but not after infection with an influenza virus." (PMID 33147208, 2020). "These interactions are modulated by TLR2 and MyD88 signaling, but not by TLR4 engagement, after intranasal or intradermal LVS infection." (PMID 32745117, 2020). "Of TLRs, we focused on TLR2 and TLR4 due to their ability to mediate inflammation not only at the interaction of bacteria with endometrial cells during infection, but also at the interaction of sperm with cumulus-oocyte complexes during fertilization." (PMID 30995239, 2019). "Because we observed that intermediate monocytes express more TLR2 and TLR4 than classical and non-classical monocytes after infection with leishmania, we analyzed the frequency of cells expressing TNF and IL-10 on monocyte subsets expressing TLR2 and TLR4." (PMID 31119102, 2019). "In contrast, using anti-TLR2 or TLR4 neutralizing antibodies, we did not observe any modulation of the inflammatory response of human keratinocytes during wild-type strain infection." (PMID 30070169, 2018).
infection (continued). "TLR2 and TLR4 are also suggested to be involved in the production of ROS and NO; however, in the context of Tc infection, TLR2/TLR4 activation appeared to be not sufficient to induce potent ROS/NO response to kill the intracellular parasite." (PMID 29503646, 2018). "This resistance to even very high-dose challenges of LVS, even in the absence of TLR2, highlights the strong effect functional Slc11a1 has the outcome of LVS infection." (PMID 28360906, 2017). "In Tm-infected mice (non-diabetic), we observed higher of levels of TLR2 expression in granulocytes and inflammatory monocytes (CD115+Ly6Chigh) at 24 and 48 h post-infection (p.i.), compared with non-infected mice." (PMID 28164040, 2017). "In contrast, treatment with ligands of TLR-2 or TLR-5 did not affect viral capture (lanes 2–3) but led to an increased productive infection of IL-4 DCs (lanes 2–3)." (PMID 28426803, 2017). "W. chondrophila stimulation of CXCL8 secretion in HEK293 cells indicates that TLR2, TLR4, NOD2 and NOD1 receptors are not essential to the innate immune response to infection." (PMID 27002636, 2016). "In our study, TLR2 (but not TLR6) was found to be up regulated in both S. aureus WCH-SK2WT and WCH-SK2SCV infection (i.e., intracellular WCH-SK2WT and WCH-SK2SCV, and extracellular WCH-SK2SCV infection)." (PMID 28083514, 2016). "The absence of either TLR2 or TLR4 significantly reduced the production of TNFα and IL6 after 24 and 48 h of infection." (PMID 28119856, 2016). "The response to specific agonists indicated that TLR2/TLR6, rather than TLR2/TLR1, is involved in the cellular reaction of HIBCPP cells following infection with N. meningitidis." (PMID 25814932, 2015). "After blocking TLR2, THP-1 cells were no longer responding to infection with S. pyogenes indicating that TLR2 was the key receptor in these cells." (PMID 25756897, 2015). "Prior to infection (0 h), no expression of IE1–72 was identified, the expression levels of TLR2 and TNF-α were low, and the expression levels of TLR4 and NF-κB were high." (PMID 25435993, 2015). "In contrast with fibroblasts, TLR2 was abundantly expressed in uninfected THP-1 and was not significantly upregulated upon infection." (PMID 25955717, 2015). "The mRNA expression of TLR1, TLR2, TLR4 and TLR6 of C. burnetii NM stimulated PBMCs derived from naive and infected goats at day 35 equalled the expression as prior infection (data not shown)." (PMID 25279829, 2014). "However, the TLR2 gene expression in this study was not regulated in MPMs nor in HBMs; hence, this result may be due to down-regulation of the OMPs previously revealed in renal tubule and urine as well as our cell infection models." (PMID 24130911, 2013). "Here, the expression of CD68, CD80, CD86, HLA-DR, MMR, TLR2 and TLR4 was analyzed under different experimental conditions (plus or minus exposure to CS, and with or without Mtb-infection)." (PMID 24278357, 2013). "Together, these results are consistent with a positive role for TLR2 and a negative role for CR3 in MAPK activation upon Schu S4 infection of human macrophages." (PMID 23359218, 2013). "Since T-cells have important roles in the control of Chlamydia, we then investigated the impact of the absence of TLR2 on adaptive CD4+ and CD8+ T-cell infiltration and activation during the later stages of infection (7 and 14 dpi)." (PMID 22724018, 2012). "Collectively, to date, the analysis of different mice strains lacking one or multiple TLR pathways demonstrated that TLR2, TLR4, TLR7, and TLR9 play a role in the resistance to infection with T. cruzi, with a degree of redundancy between them." (PMID 22496959, 2012). "Our results show, however, that in the absence of the relevant TLRs, i.e. TLR2 and TLR4, CD4+ T-cells can be sensitized to release IFNγ upon infection with C. pneumoniae." (PMID 22096480, 2011).
infection (continued). "HEK293 control cells, which do not induce TLR-2 and TLR-5 expression during infection, only secreted cytokines in small amounts, in agreement with T4SS functions being absent." (PMID 21573018, 2011). "In contrast, production of IL-12p40 by DCs following infection with mycobacteria is independent of ESAT-6 and TLR-2 expression." (PMID 22102818, 2011). "We conclude from these studies that TLR2 and MyD88, but not TLR4, play critical roles in the innate immune response to F. tularensis infection regardless of the route of infection or the subspecies." (PMID 19936231, 2009). "A recent study showed that during infection with murine CMV, virus replicates to higher levels in mice lacking TLR2." (PMID 18053251, 2007). "The absence of TLR2 and TLR4 results in impaired phagocytosis and reduced levels of TNF-α, IL-6, IL-10, and nitric oxide, which could promote a persistent infection." (PMID 41346968, 2025). "Another example is the role of TLR6 and TLR2 in the antiviral response against respiratory viral disease (RSV), where infection increases TLR2 expression and the absence of TLR2 or TLR6 leads to a higher viral load and lower production of pro-inflammatory cytokines." (PMID 40573281, 2025). "We could not observe significant differences in mb-TLR2 expression from PBMC CD4 and monocyte populations during the infection." (PMID 38140264, 2023). "The infection of GAS activates the autophagic pathway dependent on α5β1 and not on TLR2 and TLR4." (PMID 36834833, 2023). "Interestingly, they found that while TLR2/6 was involved in mice during infection with HCV, TLR1 was not involved indicating differences between human and mouse TLR2/1 or TLR2/6 in the HCV response." (PMID 36680092, 2022). "As a result, the expression of TLR2 and TLR10 experienced no obvious alterations during infection, and the expression of TLR5 and TLR6 increased slightly, whereas the expression of TLR4 was downregulated significantly, which were consistent with previous reports." (PMID 33414472, 2021). "The role of the SNPs TLR2 + 2477 G > A and CXCR5 + 10950 T > C in the severity of infection could not be confirmed in this study." (PMID 33430411, 2021). "Indeed, TLR2 and TLR4 were not necessary to reduce the growth of the pathogen following peripheral infection and to elicit the inflammatory response in the lungs following pulmonary infection." (PMID 34796128, 2021). "We also investigated the interplay between nicotine, TLR2 and TLR4 for their reported role in infection by gram-negative and -positive bacterial infection, and subsequent effect on MyD88 signaling, inflammatory response, and bacterial load in infected macrophages." (PMID 33212859, 2020). "In contrast to our findings, TLR-2 and TLR-4 are not involved in phagocytosis and ROS production in C. albicans infection although these receptors are essential to control the infection in vivo." (PMID 33193308, 2020). "Interestingly, the expression of these tolerogenic DCs was observed following infection with live MAH, but not with inactivated MAH, and when TLR2 and TLR4 were co-involved." (PMID 31440223, 2019). "Similarly, the PRV-induced inflammatory response is restricted to the area of infection, the footpad, as the virus does not activate DRG neurons to produce G-CSF and IL-6 in the absence of TLR2." (PMID 31675371, 2019). "The TLR2 surface expression level determined by flow cytometry and presented as MFI values was similar between the noninfected and Mtb-infected macrophages, which was independent of the infection time (2, 4, or 24 hours)." (PMID 31871425, 2019). "Interestingly, direct infection of isolated alveolar macrophages with PR8 also shows an increase in TLR9, TLR7 and TLR3, with no changes in TLR2, and reduced TLR4." (PMID 30682165, 2019). "Interestingly, if the animals lacked both, TLR2 and TLR9 all animals died after infection pointing out the relevance of these receptors in HSV infection." (PMID 31114761, 2019).